YAP1 (Yes1 associated transcriptional regulator)
Diseases named in the same sentence as YAP1 in open-access papers (continued):
Sharing a sentence is not in itself a finding about the gene and the disease.
ependymoma (continued). "YAP1 fusion ependymomas account for <10% of supratentorial ependymomas, are more common in females, and occur at a younger age." (PMID 36617415, 2023). "Imaging: On imaging, both ZFTA and YAP1 fusion-positive ependymomas have circumscribed margins, with solid and cystic components." (PMID 37519792, 2023). "According to the 2021 WHO classification of CNS tumors, there are two main subsets of supratentorial ependymoma, namely the ZFTA (also called C11orf95) and the YAP1 fusion positive supratentorial ependymomas." (PMID 37213274, 2023). "EET MN1-BEND2 express high mRNA levels of the ependymoma-associated genes FOXJ1, IGF2, CELSR1, RFX3, KCNJ5, TFF3 and YAP1 and relatively low levels of messages of canonical astrocyte marker genes such as OLIG2, GFAP, ALDH1L1, and S100 β." (PMID 36604386, 2023). "In YAP1 fusion-positive ependymomas, fusions of YAP1 with MAMLD1 or other partner genes are the principal oncogenic drivers of the disease through the recruitment of nuclear factor I (NFI) and TEA domain (TEAD) family domains." (PMID 37519792, 2023). "These tumors have worse survival outcomes compared to YAP-1 fusion supratentorial ependymomas, with a 10-year overall survival of approximately 50%." (PMID 37287627, 2023). "The ependymomas, YAP1‐fusion positive had similar imaging features with large tumors, peritumoral edema, and dural contact, but their contrast enhancement was weaker, and the tumors possessed central necrosis without a real cystic component." (PMID 37349135, 2023). "Supratentorial (ST) ependymomas in children have two major subgroups: RELA fusion-positive ependymoma and YAP1 fusion-positive ependymoma." (PMID 35706426, 2022). "Supratentorial ependymomas are made up of ST-sub-ependymoma and two subgroups, defined by characteristic oncogenic fusions (YAP1 and RELA)." (PMID 35745584, 2022). "ST-EPN-RELA usually harbors the fusion protein of C11orf95 and RELA and, in ST-EPN-YAP1 ependymoma, the transcriptional coactivator YAP1 fuses with other genes such as MAMLD1 and FAM118B, resulting in the upregulation of tumor promoting signaling pathways." (PMID 35884462, 2022). "ST ependymomas are divided into ZFTA (zinc finger translocation-associated, previously named RELA) or YAP1 (Yes-associated protein 1) fusion-positive." (PMID 35879477, 2022). "In ST-EPN-YAP1 ependymoma, transcriptional coactivator YAP1 fuses with other genes such as MAMLD1 and FAM118B and can upregulate Notch signaling." (PMID 33869004, 2021). "The current concept implies supratentorial ependymomas comprising C11orf-RELA-fused or YAP1-MAMLD1-fused ependymoma as well as subependymoma." (PMID 33481105, 2021). "The new 2021 WHO Classification of CNS tumors included two main subsets of ependymomas located in the ST space: those that have YAP1-fusions (ST-YAP1) and those that have ZFTA-fusions (ST-ZFTA)." (PMID 34944845, 2021). "RELA fusion-positive supratentorial ependymomas seem to affect older children and have a poor prognosis, whereas supratentorial ependymomas displaying YAP‐1 fusions affect children below 3 years of age." (PMID 34468789, 2021). "Lastly, the ST compartment contained the subgroups of ST subependymoma (ST-SE), ST ependymoma with YAP1 fusion (ST-YAP1), and ST ependymoma with RELA fusion (ST-RELA)." (PMID 34944845, 2021). "Clustering analysis, including one RELA+ and one YAP1+ ependymoma for comparison, revealed one PNET sample displaying clear expression of RELA+ signature genes." (PMID 34314101, 2021). "Supratentorial ependymoma with YAP1-fusion (ST-YAP1) is primarily a pediatric subgroup of ependymoma, with the median age of approximately 1 year and an age range from seven months to 51 years across studies." (PMID 34944845, 2021). "In another mouse study, ectopic expression of YAP1 led to generation of tumors with molecular and ultrastructural characteristics of human ependymoma." (PMID 34944845, 2021).
ependymoma (continued). "RNA sequencing and quantitative proteomics of mouse tumours demonstrate similarities to YAP1-fusion induced supratentorial ependymoma." (PMID 32404936, 2020). "Here the authors show that YAP1 activation in NeuroD6 positive neuronal precursor cells can induce ependymoma-like tumours in mice." (PMID 32404936, 2020). "Our study suggests that nlsYAP5SA and LATS1/2 cKO mice are valuable models of YAP1-fusion ependymoma for biological and preclinical research." (PMID 32404936, 2020). "Overall, we observed good correlation of our proteomics and transcriptomics analysis, which together strongly support that nlsYAP5S brain tumours resemble YAP1-fusion-positive ependymoma and activate known YAP target genes." (PMID 32404936, 2020). "Our results show that uncontrolled YAP1/TAZ activity in neuronal precursor cells leads to ependymoma-like tumours in mice." (PMID 32404936, 2020). "We used sections of human ependymomas with confirmed YAP1-MAMLD1 and C11orf95-Rela fusions (n = 3 patients each)." (PMID 32404936, 2020). "A recent publication showed that YAP1-MAMLD1 fusion in nestin-positive neural stem cells induce ependymoma-like tumours in mice." (PMID 32404936, 2020). "To conclude, IHC for nuclear p65‐RelA and FISH using break‐apart probes are highly valuable tools to diagnose RELA‐fused ependymomas, which show a worse outcome than ependymomas with YAP1 fusions and mixed ependymomas/subependymomas." (PMID 30325077, 2019). "An additional 10% of ST-ependymomas contain either C11orf95-YAP1, YAP1-MAMLD1, or YAP1-7AM11B and have a better prognosis with a five-year PFS of 66%." (PMID 30279357, 2018). "This subtype of ependymomas carry a typical YAP1 fusion gene primarily fused with MAMLD1." (PMID 37509034, 2023). "Fragment length distributions of RNAPII-Ser5p FFPE-CUTAC data using the on-slide protocol confirmed that the tumors yielded longer fragments than normal brain, with YAP1-FAM118b gene fusion-driven ependymomas showing the largest length increase relative to normal brain." (PMID 37739938, 2023). "YAP1 at 11q22.1, encoding for a DNA-binding Hippo pathway regulatory protein, and MAMLD1 fusions (YAP1-MAMLD1) appear to drive oncogenesis in a subset of supratentorial ependymomas occurring mostly in female infants." (PMID 36604386, 2023). "The group of ependymomas with YAP1 fusions occurs predominantly in children." (PMID 35119068, 2022). "They postulated that C11orf95 may play a driving role in the development of these supratentorial ependymomas because it was found to be fused to other transcription factors such as Yap1 leading to activation of alternative pathways other than NF-κB." (PMID 33481105, 2021). "Immunohistochemistry studies distinguished supratentorial ependymomas in the RELA-fusion-positive and the yes-associated protein 1 (YAP1)-fusion positive subgroups, the Neural cell adhesion molecule L1 (L1CAM) protein marking the first one and showing the most aggressive behavior." (PMID 32183175, 2020). "YAP1 gene fusions are found in subgroups of paediatric ependymomas." (PMID 32404936, 2020). "YAP1 gene fusions have been observed in a subset of paediatric ependymomas." (PMID 32404936, 2020). "Due to the unusual diffuse glioma or sarcoma like-histological findings in mouse YAP1 fusion tumors, a larger cohort of human ST-EPN-YAP1 tumors will need to be investigated histologically and molecularly to determine the relevance of mouse YAP1 fusion driven tumors as a model for human ependymoma." (PMID 33228790, 2020). "Importantly, by using transcriptomics analysis, we found that nlsYAP5SA brains have similar gene expression patterns to YAP1-MAMLD1 fused ependymoma and YAP1-MAMLD1 fusion induced mouse model." (PMID 32404936, 2020). "Specifically, nlsYAP5SA mouse tumours highly resemble YAP1-fusion ependymoma in gene expression." (PMID 32404936, 2020).
ependymoma (continued). "We next used our proteomics data to predict potential YAP1-fusion ependymoma-specific markers, reasoning that increased protein levels may lead to easier detection with immunostainings." (PMID 32404936, 2020). "Finally, we find that transcriptional cofactor HOPX is upregulated in mouse models and in human YAP1-fusion induced ependymoma, supporting their similarity." (PMID 32404936, 2020). "YAP1 fusion-positive supratentorial ependymomas predominantly occur in infants, but the molecular mechanisms of oncogenesis are unknown." (PMID 31477715, 2019). "Together, these results demonstrate that the YAP1-MAMLD1 fusion functions as an oncogenic driver of ependymoma through recruitment of TEADs and NFIs, indicating a rationale for preclinical studies to block the interaction between YAP1 fusions and NFI and TEAD transcription factors." (PMID 31477715, 2019). "In addition, data regarding the molecular subtype (i.e. RELA and/or YAP1 fusion) of these ependymoma samples was unavailable for the majority of cases as physicians rarely requested this specific testing." (PMID 29487694, 2018). "While ST-EPN-RELA tumors may occur in both children and adults, the remaining molecular subgroup of supratentorial ependymoma harbors recurrent fusions to the oncogene YAP1 and is enriched in the pediatric population." (PMID 27858204, 2017). "Patients with PF-B or YAP1-fusion positive ependymoma may be cured by surgery alone." (PMID 35455542, 2022). "Interestingly, NHERF1/EBP50 is a strong diagnostic marker for ependymoma in general, is an organizer of polarity structures such as ependymal cilia, and as further discussed in the ST-YAP1 section, has a domain PDZ-2 that binds to both β-catenin and YAP1." (PMID 34944845, 2021). "The two main subgroups of supratentorial ependymomas are characterized by fusions on chromosome 11 involving the coactivator RELA (nuclear factor NF-kappa-B p65 subunit) (affecting older children) or less frequently YAP1 fusions (affecting children <3 years of age)." (PMID 32103286, 2020). "Based on the ChIP-seq data from primary human ST-EPN-YAP1 specimens and nuclear accumulation of the YAP1-MAMLD1 protein in human primary tumors, we hypothesized that the transcriptional programme of YAP1 fusion-driven ependymoma is dependent on direct interaction between the fusion and TEAD TFs." (PMID 31477715, 2019). "In total, 150 RNA-bulk sequences of pediatric ependymomas were analyzed (PF-A = 125, ZFTA-RELA = 23, YAP1 = 2)." (PMID 41417285, 2025). "ST-ependymomas often exhibit specific genetic alterations, particularly ZFTA fusion and YAP1 fusion, while, PF-ependymomas typically lack gene-level changes." (PMID 40075518, 2025). "A follow-up study also identified YAP1::FAM118B gene fusions, the same seen in supratentorial ependymoma, in wild-type NF2 meningiomas." (PMID 40491864, 2024). "In the supratentorial area, ependymomas (grade 2 and 3) are subdivided between two genetic subgroups: supratentorial ependymomas, ZFTA fusion-positive and YAP1 fusion-positive, both mainly observed in children." (PMID 38581034, 2024). "Within supratentorial ependymomas, two specific, molecularly defined types have been added, based on the presence of ZFTA or YAP1 fusions." (PMID 37658995, 2024). "MAML2 has previously been reported as a gene partner for fusions in supratentorial ependymomas, ZFTA and YAP1 fusion-positive." (PMID 38581034, 2024). "YAP1 fusion–positive tumors are less common than ZFTA fusion–positive tumors, accounting for approximately 7% of supratentorial ependymomas." (PMID 37287627, 2023). "We observed somatic mutations or fusions in NF2 in 41% (7/17) of meningiomas, 5% (3/60) of ependymomas, and 25% (3/12) of schwannomas, as well as rare fusions in ERBB4, YAP1, and/or QKI in 10% (6/60) of ependymomas." (PMID 37492101, 2023).
ependymoma (continued). "These markers are more commonly found in pediatric supratentorial ependymomas, with a median age of 8 years for ZFTA fusion–positive tumors and 1.4 years for YAP1 fusion–positive tumors." (PMID 37287627, 2023). "In the pediatric population, supratentorial ependymomas comprise approximately 3% of all thalamic neoplasms and harbor either the ZFTA (C11orf95) or the YAP1 fusion genes." (PMID 37519792, 2023). "These included YAP1-MAMLD1 and YAP1-FAM118B found in ependymoma, along with YAP1-SS18, present in cervical squamous cell carcimoma and endocervical adenocarcinoma." (PMID 37296967, 2023). "Sequencing studies have shown that supratentorial ependymomas are largely driven by fusion genes, including ZFTA-RELA in ST-EPN-ZFTA and YAP1-MAMLD1 in ST-EPN-YAP1 tumors." (PMID 34762160, 2022). "Supratentorial ependymomas are divided into ST ependymomas with ZFTA (former RELA-/C11orf95–fusion positive ependymomas), tumors with a YAP1-MAMLD1 fusion, or other rare fusions." (PMID 35455542, 2022). "The RELA+ and YAP1+ marker probes hybridised to supratentorial tumours, while the PFA, PFA1, PFA2, and PFB marker probes hybridised to PF ependymomas." (PMID 34314101, 2021). "The majority of supratentorial ependymomas in children contain oncogenic fusions, such as ZFTA–RELA or YAP1‐MAMLD1." (PMID 34314101, 2021). "Supratentorial (ST) ependymomas in children have two major subgroups: RELA fusion-positive (ST-EPN-RELA) ependymoma and YAP1 fusion-positive (ST-EPN-YAP1) ependymoma." (PMID 33869004, 2021). "Since a high proportion of supratentorial ependymomas are driven by gene fusions involving ZFTA (C11orf95, most frequently fused to RELA) or YAP1, we performed mRNA sequencing of all samples with sufficient material (n = 20)." (PMID 34355256, 2021). "We identified only one YAP1+ tumour, confirmed by the presence of the YAP1‐MAMLD1 fusion, in an infant girl, indicating that this molecular type of ependymoma is relatively rare." (PMID 34314101, 2021). "For this we used a list of genes that was previously established to be differentially expressed between YAP1-MAMLD1 fusion and RELA fusion-positive human ependymoma subtypes, as well as between YAP1-MAMLD1 and C11orf95-RELA-driven mouse ependymoma models." (PMID 32404936, 2020). "YAP1/TAZ-induced mouse tumours display molecular and ultrastructural characteristics of human ependymoma." (PMID 32404936, 2020). "Here we show YAP1-MAMLD1 fusions are sufficient to drive malignant transformation in mice, and the resulting tumors share histo-molecular characteristics of human ependymomas." (PMID 31477715, 2019). "To investigate the composition of NHERF1 protein complexes in ependymoma, we screened the intracellular localization of the NHERF1 ligands moesin, NF2, PTEN, PDGFRα, EGFR, YAP1, β-catenin and PHLPP2 that have been functionally involved in primary brain tumors." (PMID 25775275, 2015). "In contrast, diffuse cytoplasmic EMA staining, as observed in these ZFTA-fusion tumors, has not been described in YAP1-fusion ependymomas." (PMID 41464145, 2025). "At the same time, the number of cases in each molecular subtype, particularly the single PFB case and the absence of YAP1-fusion supratentorial ependymomas, is small and introduces an unavoidable selection bias." (PMID 41464145, 2025). "The current WHO classification recognizes several molecularly defined entities: supratentorial ZFTA fusion-positive (ST-ZFTA), supratentorial YAP1 fusion-positive (ST-YAP), posterior fossa type A (PFA), posterior fossa type B (PFB), and rare subtypes such as spinal MYCN-amplified ependymoma." (PMID 41464145, 2025). "Ependymomas are classified by histology,location and molecular features (ZFTA/YAP1 fusions)." (PMID 41170123, 2025). "Supratentorial ependymomas are classified through ZFTA, previously known as RELA, or YAP1 fusions." (PMID 40677455, 2025).
ependymoma (continued). "Supratentorial ependymomas are classified based on specific fusion types such as ZFTA (formerly RELA) and YAP1, while subintentorial ependymomas are classified into type A and B based on methylation patterns, with type A being more common in adolescents and young adults and having a worse prognosis." (PMID 39293224, 2024). "Of note, up to 30% of supratentorial ependymomas do not harbor a ZFTA or YAP1 fusion: a careful exclusion of other potential diagnoses should be performed in these cases." (PMID 37658995, 2024). "This cohort of supratentorial PLAGL1-fused tumors highlights: 1/ the ependymal cell origin of this new neoplastic entity; 2/ benefit of looking for a PLAGL1 fusion in supratentorial cases of non-ZFTA/non-YAP1 ependymomas; and 3/ the usefulness of PLAGL1 FISH." (PMID 38581034, 2024). "A significant part of supratentorial ependymomas do not show fusions involving ZFTA or YAP1 genes and is currently classified as “Supratentorial Ependymomas, NEC”." (PMID 38544524, 2024). "Here, we will expand on four of the distinct subtypes of pediatric ependymomas; supratentorial ependymoma ZFTA fusion-positive, supratentorial ependymoma YAP1 fusion-positive, posterior fossa group A (PFA) ependymoma, and posterior fossa group B (PFB) ependymoma." (PMID 37509034, 2023). "New categories of supratentorial ependymomas include ZFTA fusion-positive and YAP1 fusion-positive." (PMID 37287627, 2023). "Those that have neither the ZFTA nor the YAP1 fusion constitute a different supratentorial ependymoma subset." (PMID 37213274, 2023). "The YAP1-MAMLD1 fusion gene delivered to mice by in utero electroporation drives tumor formation, and tumors share histological and molecular characteristics of human ependymoma." (PMID 35706426, 2022). "The remaining eight tumours lacking a RELA or YAP1 fusion presented as a heterogenous cohort, supporting our findings that paediatric ependymomas include tumours that can be classified as RELA/YAP1 fusion‐negative." (PMID 34314101, 2021). "The four RELA/YAP1 fusion‐negative ependymoma patients varied in terms of age (1–17 years old) and treatment." (PMID 34314101, 2021). "Besides ependymomas with RELA fusion, tumors with YAP1-MAMLD1 fusion were described as a second entity emerging in the supratentorial compartment of pediatric patients." (PMID 33481105, 2021). "Opposed to this model, recent publications described supratentorial ependymomas lacking RELA or YAP1 fusions." (PMID 33481105, 2021). "Within the supratentorial compartment, two molecularly defined types of ependymoma are characterized by recurrent gene fusions, one involving the gene ZFTA (formerly referred to as C11orf95, most frequently fused to RELA), and the other involving YAP1." (PMID 34355256, 2021). "The overall YAP1 expression level in human ST-EPN-YAP1 tumors was not higher than in other intracranial molecular ependymoma groups, but was higher than average in comparison with other genes within the individual tumors." (PMID 31477715, 2019). "Histopathological and molecular profile of ependymomas without evidence of RELA‐C11orf or YAP1 fusion." (PMID 30325077, 2019). "Chromatin immunoprecipitation-sequencing analyses of human YAP1-MAMLD1-positive ependymoma reveal enrichment of NFI and TEAD transcription factor binding site motifs in YAP1-bound regulatory elements, suggesting a role for these transcription factors in YAP1-MAMLD1-driven tumorigenesis." (PMID 31477715, 2019). "IHC positivity for YAP1 protein was observed in YAP‐fused ependymomas as well as in RELA‐fused ependymomas and did not allow to distinguish these two subgroups (data not shown)." (PMID 30325077, 2019). "Thirty‐four out of 40 (85%) cases were confirmed by integrated diagnoses as ependymal tumors, including 22 RELA‐fused ependymomas (71% of ependymal tumors), two YAP1‐fused ependymomas (6%), six non‐RELA/non‐YAP1 ependymomas (18%) and four ependymal/subependymal mixed tumors (12%)." (PMID 30325077, 2019).